CHI3L1 (chitinase 3 like 1)
Diseases named in the same sentence as CHI3L1 in open-access papers (continued):
Sharing a sentence is not in itself a finding about the gene and the disease.
COVID-19 (continued). "The aims of this study were to evaluate plasma CHI3L1 levels in COVID-19 patients at hospital admission and one month after hospital discharge in survivors, and to investigate whether CHI3L1 levels at onset predict adverse outcome." (PMID 35534648, 2022). "Anti-CHI3L1 also inhibits the abnormal fibroproliferative repair responses that are seen in pathologic tissue fibrosis such as that seen in lungs from patients with COVID-19 who require prolonged mechanical ventilation." (PMID 35735790, 2022). "CHI3L1 was higher in COVID-19 patients than controls (p < 0.0001)." (PMID 35534648, 2022). "We report that CHI3L1 accumulates early in COVID-19 patients." (PMID 35534648, 2022). "Altogether, our data indicate that plasma levels of CHI3L1, a major player in the host response to inflammatory threats, are increased in patients with more severe COVID-19 patients and predicts adverse outcome independently of systemic inflammation and clinical indicators of severity." (PMID 35534648, 2022). "We believe this decreased production of type I IFNs is a major contributor to the prevalence and severity of COVID-19 because it would increase the levels of circulating CHI3L1, increase the expression and accumulation of ACE2 and SPP, and augment viral infection and spread." (PMID 34747367, 2021). "Additional experimentation will be required to assess this speculation and further understand the relationships between CHI3L1 and COVID-19." (PMID 34747367, 2021). "The levels of circulating CHI3L1 correlated with COVID-19 disease severity." (PMID 34747367, 2021). "Although this study analyzed a large number of biomarkers (71biomarkers) and suggested a correlation of some with the severity of COVID-19, we did not analyze other markers associated with the severity of COVID, such as CHI3L1 and IGFALS59, CXCL8, CXCL10, and CCL2060." (PMID 36163447, 2022). "In our study, the critical COVID-19 patients were divided into three phenotypes (α, β, γ) using WFDC2, CHI3L1, and KRT19 on day 1 by latent class analysis." (PMID 36331721, 2023). "It is suggested that CHI3L1 is a major stimulator of ACE2, promotes binding and activation of SC2 S-protein-receptor, and enhances infection and the spread of COVID-19." (PMID 36331721, 2023). "The common plasma proteins that were higher in the COVID-19 patients than controls and that were higher in the late recovery group than the early recovery group for phases 1 and 2 were WFDC2, CHI3L1, GDF15, KRT19, and TNFRSF10B." (PMID 36331721, 2023). "We thus concluded that WFDC2, GDF15, CHI3L1, and KRT19 were four key proteins related to COVID-19 severity." (PMID 36331721, 2023). "The present studies highlight the importance of CHI3L1 as a stimulator of ACE2 and SPP and demonstrate that these inductive events enhance tissue inflammation and injury in COVID-19." (PMID 34747367, 2021). "The ability of CHI3L1 and IGFALS to discriminate favorable and adverse prognosis in COVID-19 patients was superior to that of the existing biomarkers." (PMID 34667241, 2021). "BMS inhibits CHI3L1 (chitinase 3-like-1) stimulation of ACE2 (angiotensin-converting enzyme 2) and SPP (viral spike protein priming proteases) and can be potentially used for COVID-19 therapy." (PMID 37631985, 2023). "Although quantification of CHI3L1 plasma levels is easy to perform through ELISA technique, it remains more expensive and time-consuming than measuring conventional biomarkers such as CRP, LDH or NLR, whose specificity for COVID-19 is however limited." (PMID 35534648, 2022). "The finding that CHI3L1 is a potent stimulator of ACE2 and SPP raises the interesting possibility that CHI3L1 may be a useful therapeutic target in COVID-19." (PMID 34747367, 2021). "Subsequent statistical analysis using ROC curves found that two putative prognostic indicators, namely CHI3L1 and IGFALS, may be useful in severe COVID-19 patients." (PMID 34667241, 2021).
COVID-19 (continued). "To further understand the interactions between CHI3L1 and SC2, we measured the levels of circulating CHI3L1 in a cohort of healthy individuals and in a cohort of patients presenting to the ED with symptoms suggestive of COVID-19." (PMID 34747367, 2021). "The ability of kasugamycin to ameliorate CHI3L1 induction of ACE2 and SPP while exerting antiviral and antifibrotic effects and augmenting type 1 immune responses suggests that it is a useful agent that can be used as a prophylactic or therapeutic in COVID-19." (PMID 34747367, 2021). "Thus, CHI3L1 is a universal, VOC-independent therapeutic target in COVID-19." (PMID 35735790, 2022). "CHI3L1 may play a role in the progression of COVID-19 through mechanisms not directly related to the extent of the host inflammatory response." (PMID 35534648, 2022). "Our studies also led us to appreciate that the levels of circulating CHI3L1 play a major role in defining the propensity for and severity of SC2 infection and contribute to the mechanisms by which aging and comorbid diseases contribute to the pathogenesis of COVID-19." (PMID 34747367, 2021).
gastric cancer (25 papers, 2017 to 2025). A primary or metastatic malignant neoplasm involving the stomach. "CHI3L1 is mainly secreted by fibroblasts and dendritic cells, and its high levels are linked to poor gastric cancer prognosis." (PMID 40108688, 2025). "Furthermore, our findings indicate that fibroblasts and dendritic cells are the principal sources of CHI3L1 secretion, a factor that is associated with poor prognosis in gastric cancer." (PMID 40108688, 2025). "This study highlights CHI3L1 as a key gene driving the progression from gastritis to gastric cancer, primarily by activating the CD44-β-catenin pathway, which enhances malignant cell traits." (PMID 40108688, 2025). "We identified 12 driver genes potentially involved in the gastritis-to-cancer transformation, with CHI3L1, MMP12, CXCL6, IDO1, and CCL20 emerging as the top five genes via a early gastric cancer diagnostic model." (PMID 40108688, 2025). "For instance, M2 macrophage-secreted CHI3L1 activated IL-13Rα2 expression of gastric cancer cells and advanced the metastasis." (PMID 38270646, 2024). "CHI3L1 levels were also significantly higher in the serum of patients with gastric cancer and BRCA compared to healthy donors." (PMID 39185402, 2024). "In breast and gastric cancer, CHI3L1 can be secreted by cancer cells or macrophages, affecting tumor metastasis." (PMID 37958973, 2023). "Macrophage M2 produces CHI3L1, which promotes the spread of breast and stomach cancer cells both in vitro and in vivo." (PMID 36980514, 2023). "In our published research, CHI3L1 binds to CD44v3 to activate the Erk, Akt, and β-catenin pathways, thereby enhancing gastric cancer metastasis." (PMID 36276655, 2022). "Then, we selected and validated three genes including THBS2, OSMR and CHI3L1 in Iranian gastric cancer patients." (PMID 33585016, 2020). "CHI3L1 secreted by M2 TAMs might activate the mitogen-activated protein kinase signaling pathway to promote the metastasis of breast and gastric cancer cells." (PMID 35328425, 2022). "Studies have suggested that the tumorigenic function of CHI3L1 correlates with the aggressive behavior of tumor cells, which can be used as an independent molecular marker to predict poor prognosis in gastric cancer patients through activation of the AKT pathway." (PMID 36615523, 2022). "Upregulation of THBS2, OSMR and CHI3L1 was verified in EMT-induced gastric cancer cell line." (PMID 33585016, 2020). "Furthermore, significant upregulation of candidate genes including THBS2, OSMR and CHI3L1 verified the role of these proteins in gastric cancer invasiveness." (PMID 33585016, 2020). "The results showed that CHI3L1 protein was localized in the stroma of gastric carcinomas." (PMID 28143526, 2017). "M2 macrophages secrete chitinase 3-like protein 1 (CHI3L1), which promotes the metastasis of gastric cancer cells." (PMID 40104507, 2025). "CHI3L1 promotes AKT3 signal during intervertebral disc degeneration and gastric cancer development." (PMID 36615523, 2022). "Even though the binding site of CHI3L1 to CD44 is not clear, it is known that CHI3L1 can bind to CD44 and cause gastric cancer cell metastasis." (PMID 34758182, 2022). "M2 macrophages-secreted chitinase 3-like 1 (CHI3L1), which could mediate mitogen-activated protein kinase pathway (MAPK) signaling to promote migration of gastric cancer and BC cells." (PMID 34016964, 2021). "While CHI3L1 is known to be overexpressed in GC, its significance in gastric cancer progression and metastasis is not fully elucidated." (PMID 30165890, 2018). "A recent study showed that Chi3l1 was upregulated during gastric cancer (GC) development and that through binding to CD44, it activated Erk, Akt, and β-catenin signaling, thereby enhancing GC metastasis." (PMID 34110284, 2021).
Sepsis (25 papers, 2014 to 2025). Sepsis is defined as life-threatening organ dysfunction caused by a dysregulated host response to infection. "Chitinase-3-like 1 (CHI3L1) has also been identified as a severity marker in different causes of sepsis, with increased levels associated with severe disease, complications and mortality." (PMID 33072673, 2020). "CHI3L1 expression is induced by proinflammatory cytokines, and is associated with increased patient mortality in sepsis and other infectious or inflammatory diseases." (PMID 27812211, 2016). "Thus, RA patients may be more susceptible to sepsis due to genetic variants, and the CHI3L1 genotype (rs4950928) may be a potential locus." (PMID 38053214, 2023). "Overall, the consistent ability of CHI3L1 to differentiate sepsis from SA-AKI suggests a specific pathophysiological role in SA-AKI, warranting further investigation into its diagnostic and mechanistic potential." (PMID 40892345, 2025). "STAT6 inhibition can mitigate sepsis-induced muscle weakness by downregulating Chi3l1 levels and modulating mitochondrial dysfunction and ferroptosis." (PMID 39769202, 2024). "In patients with muscle atrophy and weakness induced by sepsis, elevated levels of Chi3l1 correlate with disease severity." (PMID 39769202, 2024). "As a scientific challenge, sepsis can be diagnosed by increased Chi3l1 levels, while downregulated Chi3l1 levels have the potential to prevent skeletal muscle stem cell injury in sepsis." (PMID 39769202, 2024). "On the other hand, CHI3L1 levels in CLWH were lower than in patients with severe acute infections including sepsis (median > 1000 μg/L), SARS-CoV-2 (361 μg/L), and severe malaria (200 μg/L)." (PMID 36560606, 2022). "A recent study pointed out that the downregulation of CHI3L1 alleviates skeletal muscle stem cell injury, suggesting its therapeutic potential for sepsis." (PMID 33132754, 2020). "Interestingly, CHI3L1 was the only protein in our panel that consistently distinguished SA-AKI from sepsis across two patient cohorts." (PMID 40892345, 2025). "Our findings reveal markers of the microvascular response to sepsis, which include increased levels of HP, C3, Chil3/CHI3L1, and MMP8, both at the transcriptomic level in mouse and human kidney microvasculature and at the protein level in circulating plasma of SA-AKI patients." (PMID 40892345, 2025). "Other biomarkers, such as urinary chitinase-3-like protein 1 (u-CHI3L1) for early detection of (sepsis-induced) acute kidney injury (AKI), and plasma growth differentiation factor-15 (GDF15) for abdominal sepsis, are also typically used, along with various others." (PMID 40681771, 2025). "Moreover, previous cohort studies have documented the ability of CHI3L1 to predict outcome in infectious and inflammatory diseases, highlighting this protein as an inadequately studied modulator of sepsis." (PMID 36572854, 2022). "Circulating protein levels were elevated in sepsis and SA-AKI patients compared to controls; however, only CHI3L1 and MMP8 showed significantly higher levels in SA-AKI versus sepsis across both early and advanced stages." (PMID 40892345, 2025). "Using RT-qPCR, we confirmed the upregulation of HP, C3, Chil3/CHI3L1, and MMP8 in renal microvascular compartments in both CLP-sepsis mice and human post-mortem kidney biopsies from patients with SA-AKI." (PMID 40892345, 2025). "CHI3L1 is a relatively new biomarker of AKI or altered renal function that has been investigated in the context of critical illness, and sepsis." (PMID 29448936, 2018). "TNF, IL-18, IL-10, IL-1Ra and s-CHI3L1 were significantly higher in the septic shock group, compared with the sepsis and non-sepsis groups." (PMID 40681771, 2025). "Upregulation of HP, C3, Chil3/CHI3L1, and MMP8 in renal microvascular compartments of both mice and humans may reflect endothelial activation in sepsis, as supported by prior transcriptomic and proteomic studies." (PMID 40892345, 2025).
Sepsis (continued). "Therefore, all measured proteins showed elevated circulating plasma levels in patients with sepsis or SA-AKI, with CHI3L1 and MMP8 having distinguishably higher levels in SA-AKI compared to sepsis in both early-stage sepsis and advanced-stage sepsis." (PMID 40892345, 2025). "In the ICU cohort, which represented more advanced sepsis, levels of CHI3L1 (median 392 vs. 985 ng/mL, P < 0.01) and MMP8 (median 23 vs. 98 ng/mL, P = 0.05) were significantly higher in patients with SA-AKI compared to those with sepsis." (PMID 40892345, 2025). "At least in this model, anti-CHI3L1 treatment did not appear to alter the likelihood of fatal PA14 septicemia due to entero-hematogenic translocation, possibly due to ineffective antibody binding to CHI3L1 expressed on enteric epithelial surfaces." (PMID 26528713, 2015). "Therefore, HP, C3, Chil3/CHI3L1, and MMP8 have established roles in immune modulation, inflammation, and the oxidative stress response, and our study demonstrates their upregulation as part of the endothelial activation signature in sepsis." (PMID 40892345, 2025). "Furthermore, quercetin decreases the serum levels of Chi3l1 and periostin in cecal ligation and puncture-induced acute lung injury (ALI) rats, suggesting that quercetin may be a useful therapeutic reagent for sepsis-induced ALI." (PMID 39769202, 2024). "This may account, e.g., for the reduced rather than increased expression of the granule gene CHI3L1 in sepsis and SIRS CD15+ cells." (PMID 35844509, 2022).
inflammatory bowel disease (23 papers, 2010 to 2025). A spectrum of small and large bowel inflammatory diseases of unknown etiology. "There is growing evidence showing that CHI3L1 plays a critical role in inflammation, proliferation, and angiogenesis, and is associated with a lot of diseases including rheumatoid arthritis, liver fibrosis, inflammatory bowel disease, and neurological diseases." (PMID 33222690, 2020). "In inflammatory bowel disease, CHI3L1 aggravates inflammation and promotes bacterial adhesion and invasion by interacting with bacterial chitin-binding proteins." (PMID 40443529, 2025). "Nevertheless, CHI3L1 is highly expressed in the intestinal mucosa of patients with inflammatory bowel disease and can be used as a serum marker of this disorder." (PMID 39480684, 2024). "Conversely, CHI3L1 expressed by intestinal epithelial cells during inflammatory bowel disease helps facilitate enteric bacterial infection." (PMID 39268542, 2024). "The role of CHI3L1 in intestinal inflammation has also been studied; CHI3L1 levels were found to be significantly elevated in faecal samples from patients with ulcerative colitis and in the inflamed mucosa of patients with inflammatory bowel disease." (PMID 39480684, 2024). "CHI3L1 exacerbates intestinal inflammation and the development of inflammatory bowel disease." (PMID 39480684, 2024). "CHI3L1 activates the Protein Kinase B(AKT) and phosphoinositide-3 kinase signaling pathway, which is associated with various disorders such as pneumonia and inflammatory bowel disease." (PMID 33468116, 2021). "Interestingly, expression of CHI3L1 has been suggested to enhance bacterial adhesion and invasion into tissues via binding to bacterial chitin-binding proteins (CBPs) in both inflammatory bowel disease and burn models." (PMID 28135303, 2017).
myocardial infarction (22 papers, 2009 to 2025). Gross necrosis of the myocardium, as a result of interruption of the blood supply to the area, as in coronary thrombosis. "Studies in patients with acute myocardial infarction show that CHI3L1 plasma levels increase compared to healthy age‐matched controls." (PMID 40013912, 2025). "However, it remains unknown if CHI3L1/PAR2 signaling also mediates exercise-induced cardioprotection after myocardial infarction." (PMID 35625766, 2022). "In patients with myocardial infarction (MI), serum Chi3l1 levels greatly increase, which correlates with the levels of C-reactive protein, matrix metalloproteinase-9, and brain natriuretic protein; diastolic dysfunction; and long-term increased overall mortality." (PMID 39769202, 2024). "Another study promoted a role for CHI3L1 in promoting angiogenesis in myocardial infarction; however, those studies investigated only CHI3L1's potential to drive angiogenesis in vitro and not natively in hearts post‐MI." (PMID 40013912, 2025).